CD4 (CD4 molecule)
Diseases named in the same sentence as CD4 in open-access papers (continued):
Sharing a sentence is not in itself a finding about the gene and the disease.
interstitial lung disease (21 papers, 2011 to 2025). A diverse group of lung diseases that affect the lung parenchyma. "Here, we aimed to quantify and functionally characterize circulating topoisomerase I (topo-I)-specific CD4+ T cells and to define their association with presence and progression of interstitial lung disease (ILD) in patients with scleroderma." (PMID 27145754, 2016). "IPF is a progressive interstitial lung disease characterized by autoreactive CD4 T cells, and abnormalities in multiple pathways involved in wound healing and inflammation lead to IPF." (PMID 38504175, 2024). "An elevated TIGIT+CD226+ CD4 subset with enhanced effector function was observed in patients with DM, especially the patients complicated with interstitial lung disease." (PMID 33413573, 2021). "An increased specific CD4+ T cell subtype (CD4+CXCR4+ T cell) was significantly associated with the severity and mortality of idiopathic inflammatory myopathy-associated interstitial lung disease." (PMID 33959573, 2021). "The reason for the higher incidence and mortality may be related to the lower CD4+ T cell counts and progressive interstitial lung disease in MDA5+ patients." (PMID 34481528, 2021).
iron deficiency (21 papers, 2010 to 2025). "Activated T cells have a high demand for iron, and iron deficiency inhibits T cell proliferation, whereas iron overload leads to an imbalance in the ratio of CD4 and CD8 T cells." (PMID 36466094, 2022). "Iron deficiency anaemia is associated with a low CD4:CD8 ratio which improves on iron supplementation in children." (PMID 35022106, 2022). "To assess the impact of iron deficiency on Th17 CD4+ T-cells we used an in vitro iron deficiency model of Th17 polarisation in which iron is titrated into iron depleted media in the form of iron-saturated transferrin (Tf), known as holotransferrin (holoTf)." (PMID 34880854, 2021). "CD4+ lymphocytes are affected by iron deficiency which prevents the development of immune response against different pathologic challenges." (PMID 29433459, 2018). "In fact, SLE patients suffer from reduced iron stores and insufficient iron availability due to absolute and functional iron deficiency, which can cause mitochondrial dysfunction and ultimately affect the CD4+ and CD8+ T-cell functionality, among other metabolic pathways." (PMID 38003490, 2023). "Iron is essential for proliferation and activation of CD4+ helper T-lymphocytes and intracellular iron deficiency could impair the function of the enzymes that drive the metabolic and redox reactions involved in these processes." (PMID 35022106, 2022). "The results revealed that 0 mg FeDex and 800 mg FeDex increased lymphocytes, CD3+ T cells and CD8+CD4− T cells in MLN, suggesting that iron deficiency and iron overload promoted T-lymphocyte activation and facilitated the differentiation of CD8+ T cells in MLN." (PMID 39127747, 2024). "Iron deficiency during later childhood (< 15 years) has been shown to significantly reduce CD4+ T-cell numbers and decrease CD4:CD8 T-cell ratios without impacting IgA, IgM or IgG levels." (PMID 36267902, 2022). "cART improved CD4+ and CD8+ cell counts and their ratio, but this effect was significant only in group A. Only these patients had mild iron deficiency at T0 and showed higher transferrin and lower percentage of transferrin saturation than patients of group B, but differences disappeared with cART." (PMID 29258550, 2017). "We identified iron-interacting proteins in CD4+ and CD8+ T-cell proteomes that were differentially expressed during activation, suggesting that pathways enriched with such proteins, including histone demethylation, may be impaired by iron deficiency." (PMID 34880854, 2021).
Kawasaki disease (21 papers, 2008 to 2025). A rare inflammatory disease characterized by an acute febrile, systemic, self-limiting, medium-vessel vasculitis primarily affecting children. "This suggests that lower CD4+ cell counts are associated with a reduced likelihood of responding to IVIG treatment in Kawasaki disease patients." (PMID 41567390, 2025). "The specific contribution of CD4+ T cell subsets in Kawasaki disease is still being investigated, and further research is needed to understand their exact roles in disease pathogenesis." (PMID 37841239, 2023). "Several studies have shown alterations in the subset distribution and function of CD4+ T cells in Kawasaki disease patients." (PMID 37841239, 2023). "For example, we observed decreased B1 B-cell and CD16+ monocyte lineages as well as increased plasma cell and CD4+ T native lineages after IVIG treatment for acute Kawasaki disease patients." (PMID 36747625, 2023). "T cells CD4 memory activated, monocytes, neutrophils, and so forth were highly expressed in Kawasaki disease samples." (PMID 33188570, 2021). "In the Kawasaki disease group, the percentage of CD4+ T cells was increased and the percentage of CD8+ T cells decreased relative to the corresponding percentages in controls, leading to a significant increase in the CD4/CD8 ratio in the KD group." (PMID 33622252, 2021). "IL-35 suppressed CD14+ monocytes induced naïve CD4+ T cell activation in Kawasaki disease, and this process required direct cell-to-cell contact." (PMID 32276581, 2020). "On the one hand, IL-35 suppressed CD14+ monocytes induced naïve CD4+ T cell activation in Kawasaki disease in a direct cell-to-cell contact manner." (PMID 32276581, 2020). "Elevated circulating IL-35 played an important immunosuppressive role to CD14+ monocytes function in Kawasaki disease, including direct cell-to-cell contact-mediated naïve CD4+ T cells activation/differentiation and granzyme B-induced cytolytic function." (PMID 32276581, 2020). "Recently, increased expression of CD40L in CD4+ T cells as well as soluble CD40L was found in patients with Kawasaki disease and the levels correlated with coronary artery lesions." (PMID 28114998, 2017). "CD4+ T cells play a crucial role in the immune response and are involved in Kawasaki disease." (PMID 37841239, 2023). "Notably, lymphoid αROIs of both Kawasaki syndrome and COVID-toes exhibited a significantly higher proportion of CD4+CD57low T cells than that of patients with SLE." (PMID 37285432, 2023). "The dysregulation of CD4+ T cell subsets in Kawasaki disease suggests an imbalance in the immune response, which may contribute to the excessive inflammation and vascular damage observed in the disease." (PMID 37841239, 2023). "Therefore, we performed re-clustering of CD4+ T cells from Kawasaki disease patients, including the CD4+ naïve T cells, Th2 cells, and Treg cells." (PMID 37841239, 2023). "In Kawasaki’s disease, a medium vessel vasculitis targeting the coronary arteries, aberrant expression of miR-155 and dysregulated STAT5 signaling have been implicated in undermining CD4+ Treg function." (PMID 35296082, 2022). "IL-35 also dampened CD14+ monocytes-induced naïve CD4+ T cells activation in Kawasaki disease, indicating that elevated IL-35 might play a protective role to suppress extensive adaptive immune response in Kawasaki disease." (PMID 32276581, 2020). "In consistent with these previous reports, we found that CD14+ monocytes from patients with Kawasaki disease only effectively promoted the activation and differentiation of naïve CD4+ T cells into IFN-γ-producing Th1 and IL-17A-producing Th17 cells under direct contact condition." (PMID 32276581, 2020). "Based on these theories, reducing the level of IFN-γ and preventing these kinds of CD4 + CXCR3+ T cells from infiltrating the coronary arterial wall may be useful in the treatment of Kawasaki disease and prevention of CALs." (PMID 30704426, 2019).
Kawasaki disease (continued). "In defervesce phase of the disease, the number of CD4+CD25high regulatory T cells in patients with Kawasaki disease increases to/or above normal levels, while CD4+CD25high regulatory T cells in patients with infectious febrile disease decrease to normal levels." (PMID 19046457, 2008). "The elevated plasma levels of pro-inflammatory cytokines in Kawasaki disease are accompanied by elevated levels of anti-inflammatory cytokine IL35, which suppresses the ability of CD14+ monocytes to activate naive CD4+ T cells and has a protective effect." (PMID 36104441, 2022). "The clinical features, cytokine profile, lower naïve CD4 T cell numbers, and presence of autoantibodies place MIS-C at the intersection of severe COVID-19 infection and Kawasaki disease." (PMID 35336791, 2022). "Using the diagnosis of Kawasaki disease as the dependent variable, the variables with significant differences from univariate analysis, including IgA, IgM, IgG, absolute counts of CD3, CD4, CD8, CD16CD56 cells, and the CD4/CD8 ratio, were selected as independent variables." (PMID 41567390, 2025). "RBC, HB, CK, CK-MB, ALB, A/G, LC3II, ATG16L1 were positively correlated with BECN1; the incidence of IVIG-resistant Kawasaki disease, length of stay, lymph node enlargement, perianal desquamation, CAL, IL-4, IL-6, CRP, PCT, SF, CD3 + CD4 + T, and r-GT were negatively correlated with BECN1." (PMID 38114939, 2023). "TFH cells were reduced in SARS-CoV-2 infected children, both with and without MIS-C, but not in Kawasaki disease patients, while CD4 + effector T cells were higher in children with MIS-C than in the patients with Kawasaki disease." (PMID 36361640, 2022). "Immune imbalance in CD4 and CD8 lymphocytes were detected in acute-phase Kawasaki disease." (PMID 33622252, 2021).
alopecia (20 papers, 2010 to 2025). Hair loss usually from the scalp. "Beyond that, the observation that CD4 loss results in SC expansion and alopecia additionally suggests that CD4+ cells and their progeny are essential for maintaining SC balance in aged skin." (PMID 39905055, 2025). "Experiments in which CD4+ T cells from AA‐affected mice were injected subcutaneously into C3H/HeJ mice induced generalized alopecia in the recipients." (PMID 40260013, 2025). "One reason for this outcome is that as the disease progresses, the number of Treg cells decreases at the site of alopecia, leading to an increase in CD4+ and CD8+ T cells around the hair follicles." (PMID 40529372, 2025). "Similarly, research on the Dundee experimental bald rat model of AA has identified a potential effector role of CD4+ T cells in alopecia induction." (PMID 40260013, 2025). "Additionally, in scalp and serum biopsies from patients with frontal fibrosing alopecia, a type of scarring alopecia, differentially expressed genes related to CD4+ T helper type 1 (Th1) cells, fibrosis, T-regulatory cells, and JAK were discovered." (PMID 40497955, 2025). "In line with our results, activated CD4+ T-cell infiltrates around the lower portions of the infundibulum have been found in specimens from the transitional area of patients with progressive alopecia." (PMID 39201715, 2024). "Several immune cells, including B, CD4+ T, CD8+ T, Treg and mixed immune cells exhibited strong linkage with clinical factors, such as SS, fever, alopecia and connective tissue diseases (CTD)." (PMID 40379615, 2025). "describes the dynamics of autoreactive CD4+ and CD8+ T-cells, immune privilege guardians and IFN-γ involved in the development of alopecia, and the hair follicle growth cycles." (PMID 38550585, 2024). "Accordingly, depleting CD8+ T cells from the graft or transplanting CD4+ T cells alone reduces GVHD lethality and leads to chronic symptoms like alopecia." (PMID 39543777, 2024). "Targeted therapies that can induce alopecia include multikinase inhibitors, BRAF inhibitors, FGF inhibitors, hedgehog inhibitors, and CD4 inhibitors." (PMID 37925388, 2023). "One study reported an increased CD4+/CD8+ ratio in AU patients, but not in those with patchy alopecia, but they didn’t observed significantly decrease of CD4 T cells and CD8 T cells in blood." (PMID 40529372, 2025). "Indeed, a very recent GVHD study demonstrates that NOG mice transplanted with human CD4+ T cells (but not CD8+ cells) from PBMC develop serious skin phenotypes, alopecia, weight loss and death." (PMID 28955032, 2017). "Similarly, in the present study we found 5 (29%) cases with significant CD4+ T‐cell folliculotropism resembling FMF, however, these cases did not present with the typical clinical findings of FMF (scaly patches, acneiform lesions, alopecia, or eyebrow involvement) nor progressed like FMF." (PMID 37275409, 2023).
demyelination (20 papers, 2007 to 2025). "These include the CD8 epitope VP2121‐130 which is critical for viral clearance in resistant mice and the CD4 epitope VP274‐86 which has been shown to contribute to TMEV‐induced demyelination in susceptible strains of mice." (PMID 17388949, 2007). "The current study investigated the effects of cuprizone-induced demyelination and subsequent nanoformulation-based treatments on the expression of T-cell markers CD4 and CD8, which are key indicators of helper and cytotoxic T-cell activity, respectively." (PMID 41155593, 2025). "By presenting myelin antigen to CD4+ T cells, ImOL induce their own death, contributing to demyelination." (PMID 35615276, 2022). "Specifically, activated CD4+ T cell subsets produce a large number of inflammatory mediators, such as ROS, which induces subsequent oxidative stress and inflammatory demyelination in EAE." (PMID 33362775, 2020). "Experimental autoimmune neuritis (EAN) is a common animal model for GBS, which represents a CD4+ T cell-mediated inflammatory autoimmune demyelination of the peripheral nervous system (PNS), and is used to investigate the pathogenic mechanism of GBS." (PMID 29853789, 2018). "Univariate analysis revealed that the factors impacting the prognosis of CM patients were age, altered mentation, demyelination, CD4/CD8 ratios < 1 and CSF CrAg ≥ 1:1024." (PMID 28068915, 2017). "Here, we demonstrate that peripheral CD4+CD28null T cells are increased in EAE animals and that the percentage of CD4+CD28null T cells is strongly correlated with the amount of demyelination and disease severity." (PMID 28386103, 2017). "This study demonstrates the activation and kinetics of SR CD4+ T cells within the endogenous T cell repertoire relative to self-Ag presentation by APC following JHMV-induced demyelination." (PMID 26559484, 2015). "Both CMV infection and CD4+CD28null T cells aggravate autoimmune mediated CNS inflammation, since EAE disease severity, measured by EAE score and the extent of neuroinflammation and demyelination, correlated with increasing amounts of CD4+CD28null T cells and the presence of a CMV infection." (PMID 28386103, 2017). "Moreover, we show that the CD8+ T cells played a more significant role in HSV-IL-2 induced demyelination than the CD4+ T cells." (PMID 21364747, 2011). "In contrast to CD4+ T cell transfer, both naive and effector CD8+ T cells caused CNS demyelination in HSV-IL-2 infected mice, whereas in KOS-infected mice only effector CD8+ T cells caused demyelination." (PMID 21364747, 2011). "In our study, we observed that 12-month-old EAE mice, despite having higher numbers of infiltrating CD4+ and CD8+ T cells in the CNS, exhibited less severe demyelination compared to the younger groups (3- and 6-month-old)." (PMID 40227512, 2025). "It has been shown that in the CNS both CD4+ and CD8+ T cells are involved in the development of demyelination as a result of production by these cells of pro-inflammatory cytokines IFN-γ and TNF-α." (PMID 37153635, 2023). "Transfer of GKO memory CD4+ T cells into infected SCID mice induced rapid mortality compared to recipients of WT memory CD4+ T cells, despite similar virus control and demyelination." (PMID 22642802, 2012). "In contrast, evidence for involvement of both CD4+ and CD8+ T cells in the HSV-IL-2-induced demyelination was observed using knockout mice, depletion studies and transfer studies." (PMID 21364747, 2011). "The results of these studies provide further evidence that both CD4+ and CD8+ T cells contribute to CNS demyelination with CD8+ T cells playing a more prominent role than CD4+ T cells." (PMID 21364747, 2011). "Previously we have shown that both CD4+ and CD8+ T cells are involved in CNS demyelination." (PMID 36817487, 2023). "Similarly, no demyelination was detected in mice infected with the parental virus that were depleted of both macrophages and CD4+/CD8+ T cells (parental virus)." (PMID 28542613, 2017).
demyelination (continued). "To directly address whether T cells contribute to HSV-1-induced demyelination in the absence of macrophages, we depleted wt mice of macrophages and CD4+/CD8+ T cells or mock depleted prior to infection with HSV-IL-2 or parental virus." (PMID 28542613, 2017). "Specifically, MS-like lesions developed in the brain that included equal numbers of IFN-γ producing CD4+ and CD8+ T cells and demyelination, none of which is observed in MOG induced EAE." (PMID 26356194, 2015). "The double labeling experiments with CC1/MBP and CD4 showed CD4+ cells were abundantly distributed in the white matter upon EAE induction (arrowhead), and were specifically localized to demyelination lesions, while CC1+ OLs were absent from these areas." (PMID 22912731, 2012). "HSV-IL-2-infection of the BALB/c mice that had been depleted of their CD4+ T cells, but not their CD8+ cells, resulted in demyelination in the ON, SC, and brain, which was detected as the pale blue area in LFB staining (Arrows)." (PMID 21364747, 2011). "No demyelination was observed in ON, SC, and brain of CD4 knockout mice (CD4−/−) or CD8 knockout mice infected with HSV-IL-4 (CD4−/−)." (PMID 21364747, 2011).